NFASC (neurofascin)
Diseases named in the same sentence as NFASC in open-access papers (continued):
Sharing a sentence is not in itself a finding about the gene and the disease.
neurodevelopmental disorder (6 papers, 2019 to 2025). A behavioral and cognitive disorder with onset during the developmental period that involves impaired or aberrant development of intellectual, motor, or social functions. "Homozygous variants in NFASC lead to a neurodevelopmental disorder that includes—in some families—a chronic demyelinating neuropathy." (PMID 31501903, 2019). "Moreover, interesting risk factors for neurodevelopmental disorders were newly identified in the brain soluble fraction sheddome such as Neurofascin (NFASC), Myelin-associated protein (MAG), or Latrophilin 3 (ADGLR3), among others." (PMID 38962061, 2024). "NFASC mutations have recently been associated with neurodevelopmental disorders." (PMID 35436702, 2022). "Loss of a specific isoform of NFASC (NF155) leads to disorganization of the paranode and causes a severe neurodevelopmental disorder." (PMID 36996106, 2023). "Abnormal expression of NFASC leads to neurodevelopmental abnormalities, including neurodevelopmental disorders and demyelinating neuropathy in the central and peripheral." (PMID 37786892, 2022).
tumor (6 papers, 2014 to 2025). "Moreover, high‐risk genes identified in our model, such as NFASC, may influence tumor behavior and treatment sensitivity by modulating the TME." (PMID 41190221, 2025).
cancer (4 papers, 2017 to 2025). A tumor composed of atypical neoplastic, often pleomorphic cells that invade other tissues. "Genes such as RLIM, FBL17, FGF7, DDX5, NAV3, and NFASC were found at the intersection of multiple pathways, suggesting they may function as critical effectors of miR-155 and miR-3173 activity in cancer." (PMID 40722677, 2025).
kidney diseases (1 paper, 2024). "Co-localization of neurofascin with podocyte markers in glomerular crescents indicates its potential involvement in podocyte injury and the pathogenesis of kidney diseases." (PMID 39519211, 2024).
nervous system diseases (1 paper, 2022). "Therefore, NFASC plays a vital role in the development and function of central and peripheral nervous systems, and its dysfunction may lead to nervous system diseases." (PMID 37786892, 2022).
NFASC also shares sentences with these, for which no sentence is quoted: infection (4 papers); peripheral neuropathy (4); autism (2); CNS cancers (2); hepatocellular carcinoma (2); psychiatric disorder (2); Tremor (2); adenoma (1); alcoholic liver diseases (1); Alzheimer disease (1); amyotrophic lateral sclerosis (1); Areflexia (1); atherosclerosis (1); autism spectrum disorder (1); Autoimmunity (1); bacterial infection (1); breast tumours (1); carpal tunnel syndrome (1); cerebellar ataxia (1); Cirrhosis (1); depression (1); developmental delay (1); endotoxemia (1); epilepsy (1); facial neuropathy (1); glioblastoma multiforme (1); glioma (1); Hypertension (1); Krabbe disease (1); language delay (1).
A further 32 diseases each share a sentence with NFASC in 1 paper.